CRP (C-reactive protein)
Diseases named in the same sentence as CRP in open-access papers (continued):
Sharing a sentence is not in itself a finding about the gene and the disease.
Sepsis (continued). "Congruently, risk alleles associated with increased nuclear factor κB (NF-κB) activation upon TLR1 stimulation in previous studies, were related with reduced interleukin-10 and elevated C-reactive protein serum levels during the first week of sepsis development." (PMID 21048935, 2010). "Rapid immunological techniques like C-Reactive Proteins (CRP) assays may help in the diagnosis of septicemia; however they lack the capacity to detect specific pathogens and are not available in many centers in developing countries." (PMID 20525358, 2010). "During the last decade different biochemical markers of sepsis – C reactive protein (CRP), procalcitonin (PCT), inflammatory cytokines and acute phase reactants have been successfully studied and used in clinical practice in determining the onset of sepsis and quantifying the response to therapy." (PMID 19344519, 2009). "Elevation of C – reactive protein (CRP) has been a useful marker of sepsis in many studies." (PMID 19152691, 2009). "Therefore, the diagnosis of sepsis is often based on the development of clinical signs, in combination with laboratory tests such as a rise in C – reactive protein (CRP)." (PMID 19152691, 2009). "However, since five of these patients ended up with the diagnosis of sepsis based on clinical judgements and a rise in CRP, contamination seems less likely." (PMID 19152691, 2009). "Levels were higher in sepsis than in non-sepsis patients with a clear association to markers of the inflammatory response including white blood cell count, CRP, procalcitonin, and with the proinflammatory cytokines IL-6, IL-10, and TNF-α." (PMID 19545363, 2009). "CRP is the most commonly used marker for identifying neonates with sepsis." (PMID 19152691, 2009). "Especially serial measurements of CRP are highlyspecific and sensitive in newborn sepsis." (PMID 19043563, 2008). "However, SAA, PCT, TNF-α, IL-1β, and CRP were serially measured on days 0, 4, and 8 in the patients and once in the controls.Töllner's sepsis score (TSS) was calculated for each patient." (PMID 19043563, 2008). "Although in this study, procalcitonin seems to be an interesting marker of neonatal sepsis (early PCT peak compared with CRP), data to estimate diagnostic reliability are lacking." (PMID 16709255, 2006). "In our study CRP performed better than PCT as a diagnostic marker for infection and sepsis." (PMID 16569262, 2006). "Most importantly, the moderate trauma-related increase of PCT and the rapidly declining concentrations provide a baseline value near to the normal range at an earlier time frame than for CRP, thus allowing a faster and more valid prediction of sepsis during the early period after trauma." (PMID 16356205, 2006). "Three of these studies found PCT to be a better sepsis marker than CRP." (PMID 16569262, 2006). "PCT and CRP are increasingly used as markers for the diagnosis of sepsis and infection." (PMID 16356205, 2006). "PCT, CRP, the sepsis criteria (American College of Chest Physicians/Society of Critical Care Medicine definitions), and the Sepsis-related Organ Failure Assessment score were measured at days 1–7, as well as at days 14 and 21, concluding the observation period with the 28-day survival." (PMID 16356205, 2006). "Levels of LBP, IL-6 and CRP increased progressively with increasing severity of infection/sepsis." (PMID 16569262, 2006). "PCT and CRP are widely utilized biomarkers in sepsis diagnosis, and it was observed that their expression levels were lower in the LIPUS group compared to the CLP group from 4 to 72 h after treatment, suggesting that LIPUS may have anti‐inflammatory effects during this period." (PMID 41551210, 2026). "Multiple studies have reported sensitivities for sepsis ranging between 70% and 85% and specificities between 70% and 91%, with higher accuracy in differentiating bacterial causes of systemic inflammation from non-bacterial ones compared to CRP." (PMID 41597433, 2026).
Sepsis (continued). "The correlation between REG3E and CRP concentrations was moderate when calculated across all samples with CRP measured by the new assay (n = 144; Kendall’s Tau = 0.555; 95% CI, 0.476–0.613; P < 0.001) and low within the sepsis group (Kendall’s Tau = 0.28; 95% CI, 0.081–0.466; P = 0.0207)." (PMID 40392915, 2025). "Unlike existing biomarkers like procalcitonin or CRP, which lack specificity for early sepsis, our gene signatures could enable precise risk stratification and early diagnosis within the critical first 72 h." (PMID 40724897, 2025). "Considering the importance of VA in both anti-inflammatory and proinflammatory immune functions, VAD may contribute to exaggerated inflammatory responses in sepsis, resulting in elevated infection markers such as C-reactive protein (CRP) and interleukin-6 (IL-6)." (PMID 40843069, 2025). "Serial CRP measurements may aid in the early detection of neonatal and postoperative sepsis." (PMID 40650251, 2025). "Univariate analysis revealed that RDW (OR=1.947), APACHE II score (OR=2.303), PCT (OR=1.423), IL-6 (OR=1.237), CRP (OR=1.212), cystatin C (OR=1.324), and the main source of infection (OR=1.478) were significantly associated with the development of AKI in children with sepsis." (PMID 41281283, 2025). "Additionally, while blood samples were collected within 48 h of admission, variations in sampling timing may have affected biomarker levels, particularly given the dynamic expression patterns of inflammatory mediators such as IL-6 and CRP during early sepsis." (PMID 40714984, 2025). "Regarding the comparison between clinically and documented sepsis groups, CD64% cannot discriminate between both groups as a nonsignificant difference was illustrated (p = 0.398) with low diagnostic performance for it and other studied parameters: CD64 MFI, CD11b%, CD11b MFI, and hs-CRP." (PMID 40224545, 2025). "Therefore, the dynamic monitoring of both HBP and CRP not only significantly improves the accuracy of prognostic assessments for sepsis patients but also provides clinicians with a more comprehensive tool for patient risk evaluation, potentially aiding in clinical decision-making." (PMID 40568199, 2025). "However, combining markers such as PCT, CRP, and IL-6 with clinical judgment and blood culture results may enhance early sepsis detection." (PMID 41011807, 2025). "However, positive correlations were observed between AFP and ALT, AST, and bile acids (p < 0.001, p = 0.006, and p = 0.022, respectively) in obstructive jaundice, and between AFP and WBC, neutrophils, and CRP (p < 0.001, p = 0.001, and p = 0.005, respectively) in sepsis." (PMID 41230775, 2025). "Furthermore, moCD38 demonstrated the highest AUC of 0.91 (95% CI: 0.86–0.96) for distinguishing the Sepsis group from the Surgery group, outperforming C‐reactive protein (CRP) concentrations, procalcitonin (PCT) concentrations, APACHE II scores, and white blood cell (WBC) counts." (PMID 40145840, 2025). "However, this delayed response limits the usefulness of CRP in early sepsis diagnosis." (PMID 40282303, 2025). "Compounding these risks are diagnostic limitations: ESRD patients often exhibit an attenuated febrile response, baseline leukocyte abnormalities, and uremia-induced alterations in inflammatory markers such as C-reactive protein and procalcitonin, which may obscure early sepsis detection." (PMID 41010430, 2025). "Collectively, these findings underscore that thiol–disulfide homeostasis is intricately linked with both classical (CRP, TNF-α) and emerging (IL-40) inflammatory markers, positioning it as a critical integrative biomarker at the intersection of oxidative and inflammatory cascades in sepsis." (PMID 41196905, 2025). "However, low procalcitonin, CRP, no visible signs of infection on the chest X-ray or abdominal ultrasound, and negative blood and urine cultures allowed to exclude sepsis as a cause." (PMID 40558150, 2025).
Sepsis (continued). "In contrast, the kinetics of plasma CRP followed closely the clinical course of disease in septic dogs, as concentrations were significantly above the reference range in both sepsis and nSIRS and decreased significantly over the first 4 treatment days in dogs with sepsis." (PMID 40607352, 2025). "Traditional inflammatory markers, such as C-reactive protein (CRP) and white blood cell count, lack the specificity required for early and accurate sepsis detection, particularly in the postpartum period when these markers may be elevated due to normal physiological responses." (PMID 41409941, 2025). "Our estimated cutoff value of >0.38 may be comparatively low due to the fact that the iTBI study population at the time of admission had lower CRP and higher albumin levels in comparison to, e.g., patients suffering from sepsis, pneumonia, or cancer, or patients after excessive abdominal surgery." (PMID 38791046, 2024). "However, the interpretation of elevated CRP levels in early sepsis can be complicated by preexisting conditions such as premature rupture of the fetal membranes, antenatal steroid administration, and fetal distress, which may elevate CRP levels." (PMID 39347186, 2024). "Additionally, this patient group exhibited a higher extent of chest CT lesions, necessitated longer and more intensive ICU care, showed a higher occurrence of sepsis, elevated CRP levels, more frequent pulmonary superinfections, and had increased mortality rates." (PMID 38758248, 2024). "Several recent studies have highlighted the potential prognostic markers of outcome in severe sepsis, including the central venous minus arterial carbon dioxide pressure to arterial minus central venous oxygen content ratio (Pcv-aCO2/Ca-cvO2, the CRP/albumin ratio, and lactate clearance." (PMID 38398049, 2024). "To test the hypothesis that our defined immune traits might differentiate sepsis even in settings where the CRP is low or normal, we sub-cohorted sepsis episodes into those accompanied by a CRP rise (>10 mg L−1), and those in which CRP was normal or remained low (≤10 mg L−1)." (PMID 38195661, 2024). "Therefore, evaluating serum CRP levels may be useful in conjunction with other clinical and laboratory markers of sepsis to enhance early detection efforts by prompting close monitoring." (PMID 39716257, 2024). "Thus, the CRP level remained a substantial predictive factor for sepsis in this study." (PMID 39767696, 2024). "Furthermore, the results from our random Effects GLS regression indicated as statistically significant predictors of neonatal sepsis were the white blood cell count from the first (p = 0.005) and third day (p = 0.028), and CRP values from the first day (p = 0.004)." (PMID 38255436, 2024). "The CRP level might reflect the in vivo inflammatory state in sepsis." (PMID 39459616, 2024). "Neonates with sepsis may be separated from the control group by seeing elevated levels of CRP, platelets, absolute neutrophil count, immature to total neutrophil ratio, neutrophil-to-lymphocyte ratio, and red cell distribution width, and especially higher resistin levels (all p<0.001)." (PMID 38562275, 2024). "The sepsis group had substantially higher levels of respiratory rate (breaths/min), heart rate (beats/min), body temperature (°C), leukocyte particle concentration (×109 cells/L), C-reactive protein(mg/L), procalcitonin (ng/mL), neutrophil–lymphocyte count ratio, and plaque (mmol/L) (p < 0.05)." (PMID 38472930, 2024). "Additionally, we were unable to directly compare the outcomes of the ACS model and traditional model, and we were also unable to analyze c-reactive protein and procalcitonin levels, which are widely used clinically in patients with sepsis, due to missing data issues." (PMID 39709362, 2024).
Sepsis (continued). "A statistically significant increase in the concentrations of sepsis-associated aromatic microbial metabolites (p-HPhLA, Σ3AMM) and biomarkers (CRP, PSP) in non-survivors suggests that metabolic dysfunction should be assessed for its timely targeted correction in the future." (PMID 39335614, 2024). "The primary outcome is the frequency of patients with at least one sepsis-like event, defined by any association of suspected sepsis symptoms with a level of c-reactive protein (CRP) > 5 mg/L in a negative-culture contest, from the beginning up to 48 h after discontinuation of infusion therapy." (PMID 38971756, 2024). "Currently, the diagnostic and subsequent therapeutic management of patients with suspected infection and/or sepsis depends on the physician’s experience, which is supported by a limited number of clinically established and available biomarkers, notably C-reactive protein (CRP) and procalcitonin." (PMID 38755564, 2024). "The ROC analysis for the diagnostic value of the CRP levels for the discrimination between culture-positive and culture-negative sepsis revealed significant results [AUC = 0.845 (95% CI 0.662–1.000), p = 0.002] which were better than those for ANC [AUC = 0.765 (95% CI 0.594–0.936), p = 0.02]." (PMID 37238320, 2023). "This means that in 2022, no newborns with maternal risk factors and CRP levels over 10 mg/L and without symptoms of sepsis required EOS treatment, compared to approximately 60–75 newborns per year who received antibiotic treatment in the preceding years (group 4)." (PMID 38255366, 2023). "Furthermore, the inflammatory marker NLR has a higher diagnostic value than the conventional marker CRP, indicating that they may have complementary benefits and improve the accuracy of early DFU-induced sepsis prediction." (PMID 38026334, 2023). "Thus, while we showed that COHb can be predictive of an increased risk of LOS, Varal and Dogan demonstrated an association between increased values of COHb and the diagnosis of LOS, as well as other more accurate biomarkers of sepsis, such as C-reactive protein (CRP) and procalcitonin (PCT)." (PMID 37498388, 2023). "Increased values of CRP (OR: all = 1.276, SIC-negative = 1.616), blood glucose (OR: all = 1.370, SIC-negative = 1.315) and Hb (OR: all = 1.316, SIC-negative = 1.425) are positively associated with the development of AF in the overall sepsis and the SIC-negative cohorts." (PMID 37780563, 2023). "Finally, a meta-analysis concluded that CRP is s appropriate for detecting neonatal septicemia, and a cutoff value of 61 mg/L can be a sensitive sepsis marker that possibly promotes further inflammation via extracellular vehicles, although it is not specific [1027,1028,1029]." (PMID 37873776, 2023). "Serum CRP assays, whether performed alone or in conjunction with other relevant tests and biomarkers, play an essential role in guiding treatment decisions in neonates with suspected sepsis before receiving blood culture results." (PMID 36900011, 2023). "Additionally, CRP was found to mediate 31.53% of the effect of the genus Gordonibacter on sepsis." (PMID 37662942, 2023). "It has not been clearly identified whether CRP, procalcitonin, and presepsin could be prognostic and diagnostic markers in sepsis patients with impaired renal function undergoing CRRT." (PMID 36832265, 2023). "Similarly, the elevated cytokine response seen in GAD could contribute to the increase of CRP and IL-6, which are pro-inflammatory cytokines that are known to be significant in sepsis." (PMID 37731448, 2023). "This could be because CRP is the most sensitive and widely used test, but it is necessary to consider a sepsis panel of at least three tests, at least two of which must be positive for one to suspect septicemia with reasonable certainty." (PMID 37252936, 2023).
Sepsis (continued). "As CRP—as marker of inflammation and IL-6 activity—is a potential confounder, and inclusion of CRP in models could lead to collider bias, we re-ran our primary analyses (on sepsis incidence, sepsis-related mortality, and sepsis-related death) with and without adjusting for CRP." (PMID 37814277, 2023). "Thus, the utility of using CRP as an adjunctive diagnostic tool for diagnosing sepsis in babies with MAS is not recommended." (PMID 37814760, 2023). "In addition to the effects on the oxidative stress, bilirubin also plays a role in anti-inflammation and contributes to improve tissue injury through its anti-inflammatory mechanism in sepsis; serum bilirubin is correlated with low serum C-reactive protein levels in apparently healthy adults." (PMID 36960314, 2023). "In addition, sorting out a certain group of patients that have doubtful criteria for sepsis diagnosis and CRP below a certain threshold might impose a selection bias." (PMID 35683538, 2022). "Therefore, it may be meaningful to remove the elevated CRP levels not only after myocardial infarction but also in, for example, sepsis." (PMID 35207331, 2022). "However, few studies showed that pentraxin 3, compared to procalcitonin and CRP, did not have a diagnostic advantage in predicting sepsis in clinical practice." (PMID 35449688, 2022). "Classic pentraxins, such as CRP and serum amyloid P component (SAP), are frequently measured and recognized as indicators of inflammation; however, they provide little information regarding risk assessment and patient prognosis in sepsis caused by several infections." (PMID 35449688, 2022). "A recent analysis of 480 episodes of suspected LOS in 208 preterm infants below 32 weeks of gestational age showed that serum IL-6 and PCT levels (hazard ratios 2.28 and 2.91, respectively), but not CRP (hazard ratio 1.16), were associated with sepsis severity and mortality risk." (PMID 35345614, 2022). "Also, CRP was a better marker than PCT for sepsis induced by respiratory infection." (PMID 35907785, 2022). "Twenty two neonates had elevated CRP; 9 had fever but 13 were well with no risk for sepsis." (PMID 36407330, 2022). "However, the cut-off was not able to recognize sepsis prematurely, which is among the leading causes of death in intensive care units, due to the inadequacy of CRP and white blood cell count alone in predicting bacteremia of patients with suspected infection." (PMID 35054007, 2022). "The primary purpose of this study was to determine whether ambulation ability with albumin as a measure of nutritional status and C-reactive protein as an indicator of response to sepsis are predictive of 28-day mortality in elderly patients diagnosed with sepsis." (PMID 35962331, 2022). "Therefore, a fixed CRP cut-off value, especially for diagnosing early-onset sepsis, may ignore these physiologic changes." (PMID 36517750, 2022). "It is well known that systemic inflammation associated with elevated plasma CRP conferred a phenotype on Peripheral Blood Mononuclear Cells (PBMC), specifically through monocyte tissue factor (TF) expression by monocytes/macrophages leads to thrombin generation linked to sepsis." (PMID 34983404, 2022). "WBC and CRP levels tend to be used in this context; however, WBC was associated with low sensitivity and specificity in the present study, while CRP levels might not be suitable as a diagnostic marker in early detection of sepsis." (PMID 34065685, 2021). "Moreover, Sepsis patients had higher CRP, d‐dimer, and procalcitonin values." (PMID 33960733, 2021). "Hence, to understand the detected correlation between saliva and serum concentration of CRP in clinical studies, we collected serum and saliva samples from neonates upon onset of sepsis and during sepsis as well as saliva samples from healthy subjects for comparison." (PMID 33673378, 2021).